RNU6-985P (RNA, U6 small nuclear 985, pseudogene)
Gene: Small nuclear RNA gene on chromosome X (137,687,891 to 137,687,994, reverse strand). Ensembl gene ENSG00000222114.
Homologues: Orthologues: chimpanzee U6 (100% identical), macaque U6 (99% identical). Paralogues in human: RNU6-746P (88% identical), RNU6-1273P (87% identical), RNU6-188P (87% identical), RNU6-643P (87% identical), RNU6-1013P (86% identical), RNU6-1145P (85% identical), RNU6-1181P (85% identical), RNU6-1209P (85% identical), RNU6-15P (85% identical), RNU6-838P (85% identical), RNU6-1024P (84% identical), RNU6-1060P (84% identical), and 1286 more.